PEX11A (peroxisomal biogenesis factor 11 alpha)
Description:
May be involved in peroxisomal proliferation and may regulate peroxisomes division. May mediate binding of coatomer proteins to the peroxisomal membrane (By similarity). Promotes membrane protrusion and elongation on the peroxisomal surface.
Synonyms: HsPEX11p; PMP28; PEX11-alpha; PEX11alpha; PEX11α; MGC119947; MGC138534
Tractability: Antibody: UniProt predicts a signal peptide or a membrane-spanning region. PROTAC: ubiquitination databases record sites on it.
Gene: Protein-coding gene on chromosome 15 (89,677,764 to 89,690,783, reverse strand). Ensembl gene ENSG00000166821.
Subcellular location: Peroxisome membrane
Pathways (Reactome):
Gene expression (Transcription): MLL4 and MLL3 complexes regulate expression of PPARG target genes in adipogenesis and hepatic steatosis
Metabolism: PPARA activates gene expression
Gene Ontology:
Molecular function: protein binding; protein homodimerization activity
Biological process: peroxisome fission; peroxisome organization; regulation of peroxisome size; signal transduction; peroxisome membrane biogenesis
Cellular component: peroxisomal membrane; peroxisome; protein-containing complex
Genetic constraint (gnomAD): Loss-of-function variants: 12 observed, 13.27 expected, observed/expected ratio (o/e) 0.9, 90% interval 0.58 to 1.46. The upper end of that interval is the gene's LOEUF score, 1.46, which puts it in group 6 of 6, group 1 being the genes least tolerant of losing a copy. Missense variants: 234 observed, 260.42 expected, observed/expected ratio (o/e) 0.9, 90% interval 0.81 to 1. Synonymous variants: 86 observed, 100.17 expected, observed/expected ratio (o/e) 0.86, 90% interval 0.72 to 1.03.
Gene-disease validity (ClinGen):
ClinGen rates the evidence that PEX11A causes each of these diseases.
peroxisome biogenesis disorder (autosomal recessive): No Known Disease Relationship.
Homologues: Orthologues: chimpanzee PEX11A (99% identical), macaque PEX11A (91% identical), dog PEX11A (88% identical), pig PEX11A (83% identical), guinea pig PEX11A (83% identical), rat Pex11a (78% identical), mouse Pex11a (78% identical), tropical clawed frog pex11a (55% identical), zebrafish pex11a (48% identical), Drosophila melanogaster Pex11ab (31% identical). Paralogues in human: PEX11B (42% identical).
Diseases named in the same sentence as PEX11A in open-access papers:
PEX11A is named in the same sentence as 20 diseases in open-access papers, as found by Europe PMC text mining. Sharing a sentence is not in itself a finding about the gene and the disease. The quoted sentences say what the papers report.
Obesity (5 papers, 2019 to 2024). Accumulation of substantial excess body fat. "Understanding of the mechanisms by which Pex11a deficiency decreased energy expenditure and fatty acid oxidation and resulted in the accumulation of very long‐ and long‐chain fatty acids will be required to develop therapeutic strategies for dyslipidaemia and obesity." (PMID 30585412, 2019). "Future studies dealing with PEX11A would be advised to consider the present data in case they are based on a diet-induced obesity model." (PMID 36755289, 2023). "The role of Pex11a in dyslipidaemia and obesity is investigated here with Pex11a knockout mice (Pex11a−/−)." (PMID 30585412, 2019). "In the present study, we used Pex11a−/− mice to investigate the role of Pex11a in lipid metabolism and obesity." (PMID 30585412, 2019). "Understanding of the molecular and physiological functions of Pex11 gene and etiology of dyslipidaemia and obesity, will facilitate the development of therapeutic strategies of targeting Pex11a for dyslipidaemia and obesity." (PMID 30585412, 2019). "Importantly, Pex11a knockdown impairs physical activity and energy expenditure, leading to dyslipidemia and obesity." (PMID 39458511, 2024). "Since several studies reported that PEX11A deficiency contributes to increased triglyceride accumulation in the liver and leads to dyslipidemia and obesity in mice, PEX11A might seem worth a closer look." (PMID 36755289, 2023). "However, feeding of PEX11α KO mice with a high-fat diet resulted in impaired physical activity and energy expenditure, decreased fatty acid β-oxidation, increased de novo lipogenesis as well as dyslipidaemia and obesity." (PMID 33195217, 2020). "Furthermore, Pex11a deficiency decreases peroxisome abundance and fatty acid β‐oxidation, and increases de novo lipogenesis in BAT, which results in accumulation of very long‐ and long‐chain fatty acids, especially in sera, and then contributes to dyslipidaemia and obesity." (PMID 30585412, 2019). "In summary, the current study suggests that Pex11a is required for peroxisome proliferation in BAT and highlights the relation between Pex11a and dyslipidaemia and obesity." (PMID 30585412, 2019). "PEX11A and PEX7 were among the most upregulated peroxisome-related proteins and are essential for proper peroxisomal function and the prevention of dyslipidemia and obesity." (PMID 39280921, 2024).
dyslipidemia (4 papers, 2022 to 2024). "Furthermore, Vnn1 is expressed by the centrilobular hepatocytes and is involved in lipid and xenobiotic metabolism, whereas Pex11a (peroxisomal biogenesis factor 11 alpha) is involved in peroxisome maintenance and proliferation associated with dyslipidemia." (PMID 35935858, 2022).
peroxisomal biogenesis disorders (4 papers, 2015 to 2025). "Our study provides extensive semi-quantitative molecular information on the metabolic alterations in Pex11α KO mice, which will complement the understanding of the molecular functions of Pex11α and underlying pathophysiological mechanisms of peroxisomal biogenesis disorders." (PMID 35083512, 2022). "Overall, the present study reports comprehensive semi-quantitative molecular omics information of the Pex11α KO mice, which might serve in the future as a reference for a better understanding of the roles of Pex11α and underlying pathophysiological mechanisms of peroxisomal biogenesis disorders." (PMID 35083512, 2022). "In contrast to other peroxisomal biogenesis disorder (PBD) mouse models (such as the Pex5, Pex2, Pex13 knockout mice), which mimic the Zellweger spectrum symptoms, the Pex11a knockout mice still contain peroxisomes that harbor the typical peroxisomal marker enzymes." (PMID 41511296, 2025).
dyslipidaemia (2 papers, 2019 to 2020). "Although the mechanism how Pex11a deficiency regulates FAS needs to be further studied, Pex11a deficiency indeed results in increased de novo lipogenesis and contributes to dyslipidaemia." (PMID 30585412, 2019).
chronic kidney disease (1 paper, 2015). Impairment of the renal function secondary to chronic kidney damage persisting for three or more months. "Our previous studies have shown that Pex11a deficiency impairs peroxisome elongation and abundance and peroxisomal fatty acid β-oxidation, subsequently contributing to increased lipid accumulation in the liver (steatosis) or kidney (chronic kidney disease)." (PMID 25659146, 2015).
steatosis (1 paper, 2015). Increased lipid within the cytoplasm of cells. "We previously found that peroxisomal biogenesis factor 11a (Pex11a) deficiency is associated with a reduction in peroxisome abundance and impaired fatty acid metabolism in hepatocytes, and results in steatosis." (PMID 25659146, 2015).
infection (5 papers, 2016 to 2023). The state of being infected such as from the introduction of a foreign agent such as serum, vaccine, antigenic substance or organism. "To validate that the peroxisomal proliferation is important for infection, we deleted the PEX11A gene in the ΔModnm1, ΔMofis1, and ΔMomdv1 mutants and characterized these mutants." (PMID 27556292, 2016).
tumor (3 papers, 2015 to 2025). "In contrast, analysis for mRNAs encoding for peroxisomal biogenesis proteins (Pex7, Pex10, Pex12), and proteins for peroxisomal proliferation (Pex11α, Pex11β) were significantly upregulated in PMA tumor compared to control tissue." (PMID 34360635, 2021).
cancer (2 papers, 2015 to 2020). A tumor composed of atypical neoplastic, often pleomorphic cells that invade other tissues. "PEX11A and UPK have not been previously reported to be related to cancer." (PMID 31927533, 2020).
cardiovascular diseases (1 paper, 2025). "Elevated arginase expression, as observed in the Pex11a knockout, and higher circulating serum arginase levels exacerbate cardiovascular diseases and cardiac remodeling." (PMID 41511296, 2025).
PEX11A also shares sentences with these, for which no sentence is quoted: breast cancer (2 papers); Breast Invasive Carcinoma (1); glomerulonephritis (1); Hyperglycemia (1); Insulin resistance (1); parotid tumor (1); renal fibrosis (1); respiratory infections (1); Zellweger syndrome (1); ZIKV infection (1).